GCG (glucagon)
Diseases named in the same sentence as GCG in open-access papers (continued):
Sharing a sentence is not in itself a finding about the gene and the disease.
diabetes (continued). "These encouraging findings put into perspective the role of glucagon and α cells in diabetes treatment and demonstrate that diabetes is more than a “relative or absolute insulin deficiency”." (PMID 34502413, 2021). "Diabetes has long been recognized as a “bihormonal disorder”, characterized by glucagon excess in the setting of insulin deficiency or insulin resistance." (PMID 33494193, 2021). "Chronic dysregulation of glucagon and insulin signaling underlie the pathogenesis of type 2 diabetes mellitus T2DM, and the activities of both hormones must be studied together." (PMID 33708137, 2021). "In diabetes, loss of insulin-producing pancreatic beta-cell mass, is accompanied by dysfunction of glucagon-producing alpha cells, which fail to respond to the normal suppressive effects of glucose and insulin, leading to hyperglucagonaemia." (PMID 34081167, 2021). "The high risk of MEN1 patients developing diabetes has been considered to be caused by the production of diabetogenic hormones such as glucagon by the P-NET and/or surgical resection of the pancreas." (PMID 32884006, 2020). "Loss of β-cell function in diabetes decreases this inhibitory tone, and the glucose stimulation is less effective at reducing glucagon levels." (PMID 32964214, 2020). "While diabetes has long been linked to impaired insulin secretion, recently, glucagon has received much attention with respect to its role in diabetes." (PMID 31829209, 2019). "In support of this concept, triggering glucagon signalling deteriorates glycemia in diabetes and obesity, both of which are associated with insulin insensitivity." (PMID 30626440, 2019). "In diabetes, glucagon secretion is dysregulated but the underlying mechanisms are not fully understood." (PMID 30415925, 2019). "Similar defects in glucagon secretion develop in other diabetic models: transgenic mice that express a human neonatal diabetes mutation (Kir6.2-V59M) specifically in β cells and Goto-Kakizaki (GK) rats, a model of polygenic diabetes." (PMID 30415925, 2019). "Accurate measurement of glucagon has been essential for uncovering its pathological hypersecretion that underlies various metabolic diseases including not only diabetes and liver diseases but also cancers (glucagonomas)." (PMID 31284506, 2019). "Recently, glucagon has been recognized as a pivotal factor implicated in the pathophysiology of diabetes." (PMID 29535833, 2018). "When GABA is given to mice with T1D, it restores β cells, completely reverses the symptoms of hyperglycemia and cures diabetes, associated with elevated insulin levels and reduced glucagon levels." (PMID 30202421, 2018). "Since weight gain in diabetes has been shown to adversely affect cardiovascular risk, this has to be considered as a drawback of combining insulin and glucagon for the treatment of diabetes." (PMID 29558502, 2018). "Consistent with reduced glucagon abundance, the diabetes-associated overexpression of key gluconeogenic enzymes, glucose-6-phosphatase and PEPCK were also lowered by SRT3025." (PMID 30228292, 2018). "Liraglutide, a long-acting GLP-1 receptor agonist, is widely used for treating diabetes by stimulating glucose-dependent insulin secretion and suppressing glucagon secretion with a very low risk for hypoglycemia." (PMID 29618348, 2018). "High-glucose treatment induced increased glucagon secretion in InR1G cells, which represents a hallmark of diabetes mellitus." (PMID 28426798, 2017). "It should be noted that the mechanisms underlying glucagon dysregulation in diabetes are not completely understood, but appear to be attributable to many factors that are affected by insulin resistance and hyperglycemia." (PMID 28801559, 2017). "The mechanisms underlying dysregulated glucagon secretion in diabetes, both physiological and molecular, are still unclear." (PMID 28426798, 2017).
diabetes (continued). "In August 2016, several leaders in glucagon biology gathered for the European Association for the Study of Diabetes Hagedorn Workshop in Oxford, England." (PMID 28323959, 2017). "The significance of glucagon in the pathophysiology of diabetes mellitus is widely recognized, but the mechanisms underlying dysregulated glucagon secretion are still unclear." (PMID 28426798, 2017). "Multiple-low-dose STZ-induced diabetes was associated with diminished insulin-positive beta cells (p < 0.001), augmented glucagon-positive alpha cells (p < 0.001) and decreased GPR119 expression (p < 0.001)." (PMID 27677765, 2016). "In conclusion, although inhibition of glucagon action alone is insufficient to prevent diabetes in conditions of near-total insulin deficiency, it is beneficial when residual insulin action persists, as in STZ-treated Gcgr-/- animals." (PMID 27092792, 2016). "The mathematic model used here provides a powerful tool to investigate the cause of dysregulation of glucagon secretion seen in diabetes." (PMID 27044683, 2016). "Loss of insulin-mediated intra-islet suppression of glucagon production appears to be a contributor to the hyperglycemia of Akita mice, a model of insulin-deficient diabetes." (PMID 28702245, 2016). "The molecular events that underlie glucose stimulation of glucagon release should therefore be identified and explored as potential targets in diabetes therapy." (PMID 27044660, 2016). "We also attempt to combine the intrinsic and paracrine mechanisms using mathematical models to address the possible cause of impaired glucagon secretion seen in diabetes." (PMID 27044683, 2016). "Some research indicated that the dysfunction of sodium channels in pancreatic α cells was associated with dysregulation of glucagon secretion in diabetes." (PMID 27608006, 2016). "It is well established that the loss of insulin immunostaining seen in many mouse models of diabetes is paralleled by an increase in glucagon immunostaining." (PMID 25982967, 2015). "Excessive hepatic glucose production, a characteristic of diabetes mellitus due to insulin deficiency/resistance and elevated glucagon levels, is responsible for the fasting hyperglycemia in diabetes." (PMID 25762623, 2015). "Maneuvers that increase KATP channel activity, such as metabolic inhibition, mimic the glucagon secretory defects associated with diabetes." (PMID 24315372, 2013). "Correlation between urinary ACE2 excretion and well-established plasma risk factors of diabetes, such as triglycerides and glucagon, suggest urinary ACE2 as a novel surrogate marker for diabetes." (PMID 23646149, 2013). "Hypoglycemia is a feared complication of pancreatogenic diabetes, due to the loss of the counterregulatory mechanism offered by glucagon." (PMID 22966212, 2012). "The effects of ablation of glucagon actions on the development of insulin-deficient diabetes have been studied in glucagon receptor knockout mice (Gcgr−/−)." (PMID 23316165, 2012). "Roger Unger postulated that diabetes is caused by insulin deficiency (amount or effect) and glucagon presence, or excess." (PMID 22969729, 2012). "Additionally, the insulin signaling, glucagon signaling, and diabetes-related pathways also showed positive associations with 23-deoxycholic acid and estrone." (PMID 40731966, 2025). "In light of the documented interaction between α- and β-cells, individuals with type 1 diabetes mellitus (T1DM) exhibit increased glucagon levels as a consequence of insulin deficiency and the resulting loss of tonic inhibition normally exerted by β-cells on α-cells." (PMID 41149695, 2025). "The objective was to determine the association between serum IgE levels and the infiltration order of T lymphocytes and macrophages in pancreatic islets in relation to the loss of insulin and glucagon cells in presymptomatic congenic BB Gimap5-DP (Diabetes Prone) rats." (PMID 41042382, 2025). "Access to insulin and the duration of diabetes diagnosis were also linked to glucagon awareness." (PMID 40585626, 2025).
diabetes (continued). "Diabetes, including T1D and T2D, has long been recognized as a bi-hormonal disease characterized not only by absolute or relative insulin deficiency, but also by inappropriately high levels of its counter-regulatory hormone glucagon." (PMID 39429740, 2024). "The effect of protein and AA on glucagon secretion and circulating glucagon could be one of the mechanism underlying the observation of an increased diabetes risk associated with a high (animal) protein consumption." (PMID 39114126, 2024). "Furthermore, pancreatic inflammation leads to the decrease of islet cell mass leading to the loss of glucagon, insulin, and pancreatic polypeptide, which difficult the control of diabetes with large variations in blood glucose." (PMID 39030443, 2024). "Notably, an imbalance between glucagon and insulin production has been implicated in patients with diabetes mellitus." (PMID 38626157, 2024). "After both treatments, glucagon-positive cells were found in the core of the pancreatic islet, which was obviously a reflection of the diabetes-related destruction of pancreatic morphology linked to impaired glucagon signalling that leads to a marked increase in alpha cell mass." (PMID 39062940, 2024). "Patients with diabetes associated with CRC may have a better prognosis if high endogenous glucagon levels are present." (PMID 38072640, 2024). "Regarding the first question, diabetes possibly being secondary to glucagon excess is a reasonable hypothesis since glucagon seems to be more critical for the development or worsening of diabetes than insulin deficiency." (PMID 39309109, 2024). "At the same time, GPR119 activation also increases glucagon secretion, which may reduce the risk of medically induced hypoglycemia in patients with diabetes undergoing intensive insulin therapy." (PMID 37686185, 2023). "Despite controversy regarding the role of glucagon in metabolic disorders associated with diabetes, the recognized importance of hyperglucagonemia in the pathophysiology of T1D and T2D fostered the development of therapeutic strategies aimed at glucagon action reduction." (PMID 37008937, 2023). "While this review focuses on SST-dependent mechanisms of glucagon counterregulatory failure in insulin-deficient diabetes, other causative mechanisms, such as changes in the anatomical and paracrine relationships between α- and β-cells, may also play a role." (PMID 38298268, 2023). "Besides diabetes, a whole spectrum of metabolic complications, such as cardiovascular complications or obesity, are associated with glucagon secretion and insulin resistance because they are closely related to the control of body weight and energy consumption." (PMID 37628857, 2023). "Glucagon dysregulation and hyperglucagonemia were previously associated with pre‐diabetes and T2D." (PMID 37078380, 2023). "Currently, the mechanism by which KATP variants induce high diabetes risk remains unclear, possibly involving inadequate insulin secretion, resistance to insulin, or (and) impaired glucagon secretion." (PMID 35402560, 2022). "However, each type of diabetes in animals and humans is accompanied by hyperglucagonemia, so glucagon excess is more critical to the development of diabetes than insulin deficiency." (PMID 35784565, 2022). "Once understood, rational therapeutic approaches could be fashioned to mitigate this rise in glucagon concentrations thus reducing the risk for ketoacidosis, a potentially problematic acute complication of diabetes." (PMID 35590248, 2022). "Thus, compared with insulin deficiency, glucagon excess plays a more essential role in the development of diabetes." (PMID 35784565, 2022). "Well-established tumor-associated pathways including WNT signaling, RUNX1 signaling, and NOTCH signaling were associated with GCG expression in COADREAD, suggesting an interplay with deregulated GCG signaling, such as in altered glucose homeostasis of diabetes mellitus which is a known risk factor." (PMID 35340411, 2022).
diabetes (continued). "Whether the elevation in blood glucose is associated with a rise in plasma glucagon seems to depend on the category of diabetes." (PMID 35569125, 2022). "Inappropriate glucagon secretion after meal, which causes a large amount of liver glucose output even after meals, is an important cause of hyperglycemia in type 2 diabetes mellitus, and appropriately suppression of postprandial glucagon secretion is beneficial to postprandial blood glucose control." (PMID 36307866, 2022). "For example, by inhibiting MafF, the pancreatic beta cells loss its function in diabetes; it also regulates endoplasmic reticulum stress as well as autophagy in diffuse large B-cell lymphoma; and human glucagon expression." (PMID 35444548, 2022). "Here, we focused on the GCG gene and its derived peptide hormones, which are important in various (patho)physiological processes related to glucose metabolism and are associated with diabetes and other disorders." (PMID 34220721, 2021). "In diabetes, beta cell deficiency, together with alpha cell insulin and somatostatin resistance, all contribute to alpha cell dysfunction and a loss of the regulation of glucagon secretion, resulting in hyperglucagonemia." (PMID 34659118, 2021). "Furthermore, the severity, organ dysfunction, and mortality were seen in patients with severe sepsis who have a close relationship with high plasma glucagon levels, suggesting an association between glucagon overproduction and diabetes immune deficiency." (PMID 34295325, 2021). "Patients with diabetes mellitus exhibit hyperglucagonemia, or excess glucagon secretion, which may be the underlying cause of the hyperglycemia of diabetes." (PMID 34659118, 2021). "Impaired glucagon secretion predisposes some patients with type 1 diabetes mellitus to hypoglycemia; whereas hyperglycemia in patients with type 1 diabetes mellitus or type 2 diabetes mellitus is often associated with hyperglucagonemia." (PMID 33776655, 2021). "However, there is controversy regarding the relative importance of insulin deficiency and glucagon excess to the hyperglycemia observed in diabetes pathology." (PMID 33810265, 2021). "Our findings also suggest that glucagon level is significantly associated with abdominal obesity in type 2 diabetic subjects; therefore, glucagon-suppressive drugs for the treatment of diabetes may have a significant effect on weight management." (PMID 33758717, 2021). "In 1973, Unger and Orci presented the bihormonal-abnormality hypothesis, which states that excess glucagon could play an important role equivalent to that of insulin deficiency in the pathogenesis of diabetes." (PMID 34199839, 2021). "We believe that this knowledge contributed to a better understanding of the role of glucagon on the increased susceptibility and worsening of sepsis in diabetes, which may benefit future investigations of therapeutic strategies for septic diabetic patients." (PMID 34295325, 2021). "In this way, as Unger supported for his whole life, glucagon could regulate glycaemia level but it could be much more, it could represent the real cause of diabetes, overcoming the role of insulin and its deficiency." (PMID 34572493, 2021). "If this mechanism becomes defective in diabetes, it might explain the dysregulation of glucagon secretion associated with the disease and the loss of appropriate counter‐regulatory glucagon secretion in some of the patients." (PMID 32716554, 2020). "Furthermore, elevated levels of some neprilysin substrates (glucagon and insulin) have been described as the main cause of diabetes, and one of the symptoms associated with sickle cell disease (substance P)." (PMID 32366041, 2020). "In addition, after insulin resistance becomes severe in diabetes, excess glucagon is known to cause difficulty in controlling blood glucose 118; the relationship of these changes to reproduction is a topic for future study." (PMID 32684824, 2020).
diabetes (continued). "Recent evidence suggests mutual underlying pathologies between diabetes mellitus and neurodegeneration due to the homeostatic imbalance of glucagon–insulin in diabetes mellitus, which induces amyloid deposition in the pancreatic islets of Langerhans’s and the brain." (PMID 32085610, 2020). "This concept may – as we will elaborate below – have important implications for the understanding of the dysregulation of glucagon secretion associated with diabetes." (PMID 32716554, 2020). "Further studies are warranted to clarify the mechanisms by which alpha-cell-intrinsic glucose sensing controls glucagon secretion via cAMP, and whether aberrant cAMP signalling underlies the dysregulated glucagon secretion in diabetes." (PMID 30953108, 2019). "A recent study has shown that along with reduced insulin secretion, decreased glucagon suppression may contribute to the predisposition to diabetes conferred by TCF7L2." (PMID 30700996, 2019). "Exocrine pancreatic function has not been systematically explored, though it has been recently shown in one case of diabetes induced by nivolumab (anti-PD-1), with both a bi-hormonal deficiency (insulin and glucagon) and an exocrine pancreas insufficiency (asymptomatic reduction in fecal elastase)." (PMID 30400055, 2019). "Therefore, glucagon secretion in pancreatic α cells is controlled by other islet cells or themselves, and such mechanism is associated with the pathogenesis of diabetes." (PMID 31357734, 2019). "Taken together with this background on glucagon, we hypothesized that hyperglucagonemia is one factor that increases the risk of colorectal cancer in diabetes patients." (PMID 29535833, 2018). "The bihormonal-abnormality hypothesis combines these two findings, stating that the relative glucagon excess and insulin deficiency, plus the opposing actions of these two hormones, leads to the hyperglycaemia of diabetes." (PMID 29412829, 2018). "In diabetes, hypoglycaemia results from profound disturbances in glucose homeostasis and, in particular, the inability to ‘shut off’ exogenous insulin delivery and loss of normal physiological regulation of glucagon secretion." (PMID 29417183, 2018). "Then in 1973, Roger Unger and Lelio Orci proposed the bihormonal-abnormality hypothesis of diabetes, stating that glucagon elevation was as important as insulin deficiency." (PMID 29412829, 2018). "We hypothesized that coadministration of glucagon and insulin could reduce the risk of hypoglycemia when treating diabetes." (PMID 29595915, 2018). "Furthermore, we showed that the modified WB is applicable to other diabetes-associated peptide hormones: insulin analogs, glucagon, GLP-1s, somatostatins, ghrelins, and pancreatic polypeptide." (PMID 28761041, 2017). "In addition, her high risk of hypoglycemia was compounded by long-standing diabetes with inadequate glucagon secretion and autonomic neuropathy with hypoglycemia unawareness." (PMID 28748191, 2017). "Indeed, additional studies are still needed to explore the precise relationships between loss of beta cell insulin production, glucagon-positive cell mass, hyperglucagonemia, and the onset of hyperglycemia in insulin-deficient diabetes." (PMID 28702245, 2016). "The possibility that loss of intra-islet suppression of alpha-cells, with increased circulating glucagon, contributes to diabetes under conditions of intra-islet insulin deficiency, raises questions about effective treatments that may be available." (PMID 28702245, 2016). "Because β-cell ablation was incomplete after STZ, we aimed at determining whether the action of residual circulating insulin might, in combination with glucagon signaling deficiency, protect Gcgr-/- mice from diabetes." (PMID 27092792, 2016). "We speculate that this relative lack of α-cells might preserve the functional balance of insulin to glucagon after ongoing β-cell loss and thereby protect dogs from clinical presentation until late in the course of diabetes." (PMID 26057531, 2015).